FOXP1 (forkhead box P1)
Diseases named in the same sentence as FOXP1 in open-access papers (continued):
Sharing a sentence is not in itself a finding about the gene and the disease.
autism (39 papers, 2011 to 2025). Persistent deficits in social interaction and communication and interaction as well as a markedly restricted repertoire of activity and interest as well as repetitive patterns of behavior. "In other brain regions, key autism susceptibility genes included FOXP1 (caudate and putamen), MEF2C and SATB2 (cortical plate), and TBR1 and NR4A2 (subplate)." (PMID 41279531, 2025). "This gene also appears to regulate the FOXP1 gene, which has been linked to autism and hematologic cancers." (PMID 41228537, 2025). "Previous work has shown that early but not late neural progenitor cells (NPCs) endogenously express the autism-linked transcription factor Foxp1, and both loss and gain of Foxp1 function can alter NPC activity and fate choices." (PMID 38600346, 2024). "This study found that loss of the autism-associated gene Foxp1 in the mouse cortex leads to a slower reaction to adhesive paper and hyper-responsiveness to repeated whisker stimulation." (PMID 37691105, 2023). "Previously, variants within the functional domains of the FOXP1 protein have been associated with autism; Pariani, Spencer, Graham, & Rimoin, 2009) and more recently, FOXP1 related ID syndrome." (PMID 31111659, 2019). "Variants with at least one de novo mutant allele in the proband and with an autism‐related clinical annotation revealed rs143202281 (rs886058828) in the gene FOXP1 (chr3: 71,004,983 GCA/G, GCA/CA (Qual = 46.73)." (PMID 31111659, 2019). "FOXP1 has been linked to several cognitive disorders, and its deletion causes autism-like behaviors in mice." (PMID 28344757, 2017). "In particular mutations and deletions in FOXP1 have been shown to cause autism, mental retardation and speech and language deficits." (PMID 24690944, 2014). "In the present study, we found that increased FOXP1 gene expression was associated with autism in general." (PMID 23815876, 2013). "The present study suggests that rare, coding variants in these genes are also relevant to left-handedness, which raises the possibility that altered development of the brain’s left-right axis is part of the etiology of autism when caused by DSCAM or FOXP1 mutations." (PMID 38565598, 2024). "We previously demonstrated that early RG highly express the autism-linked transcription factor Foxp1, which promotes symmetric cell divisions and self-renewal, and sustains the potential to generate both early-born deep-layer neurons and later-born upper-layer neurons." (PMID 38600346, 2024). "In addition, the autism-associated gene FOXP1 showed significant association with left-handedness after Bonferroni correction for 43 tests for the broad set only (beta = 0.17, P = 2.3 × 10−4 uncorrected)." (PMID 38565598, 2024). "Altered levels of FOXP1 expression have been linked to abnormal neurodevelopment and autism." (PMID 31995614, 2020). "Collectively, these data suggest that HuR may regulate autism-associated Foxp1 and Foxp2 expression during neocorticogenesis." (PMID 27383233, 2016). "Recently, FOXP1 was implicated in autism, ID, and language impairment." (PMID 22102821, 2011). "Conversely, the Fawn-hooded rats are thereby similar to other autism-like preclinical models such as prenatal valproate exposure, cortex-specific deletion of Foxp1 or other genetic modifications." (PMID 39065788, 2024). "Among genes previously implicated in autism or schizophrenia by exome screening, DSCAM and FOXP1 show evidence for rare coding variant association with left-handedness." (PMID 38565598, 2024). "Conditional KO of Foxp1 in the brain leads to striatum developmental defects and autism-like behaviors in mice." (PMID 37691105, 2023). "Although no gene reached formal significance levels, it is possibly of some interest that three genes potentially related to autism were each individually significant at P < 0.001: FOXP1, ARHGAP33 and CDH9." (PMID 33893496, 2022).
autism (continued). "While rates of ASD are relatively low in this rare disorder compared to others such as tuberous sclerosis or ADNP syndrome, they are higher than some other disorders already included on clinical autism sequencing panels (e.g. FOXP1)." (PMID 35271727, 2022). "Many clinical laboratories offer clinical sequencing (whole exome sequencing and whole genome sequencing) and autism focused sequencing panels, which include the FOXP1 gene." (PMID 33892622, 2021). "For example, Foxp1 is a good example of an autism-related gene with a demonstrated striatum-specific function." (PMID 33716665, 2021). "Although there are likely to be many neuronal-specific transcriptional targets of FOXP1 repression responsible for regulating dendrite morphogenesis, one validated target is the candidate autism gene CNTNAP231." (PMID 28408745, 2017). "A 5 Mbp de novo deletion involving FOXP1 on chromosome 3p14.1 was identified in an individual with features of idiopathic autism (full-scale IQ = 75)." (PMID 22102821, 2011). "We employed cortex-specific Foxp1 knockout (Foxp1-cKO) mice as a model of autism in this study." (PMID 37691105, 2023). "No gene was formally significant after correction for multiple testing, but three genes possibly related to autism were significant at P < 0.001, FOXP1, ARHGAP33 and CDH9, along with VGF which may also be of psychiatric interest." (PMID 33893496, 2022). "Additionally, we observed an enrichment (FDR = 0.015) for candidate autism genes, including FOXP1, CUL7, ANK3, and EP300, among the differentially expressed genes." (PMID 34657631, 2021). "HIVEP2 and FOXP1 code for transcription factors and both have previously been related to autism." (PMID 35052433, 2021). "Remarkably, the autism-linked CNTNAP2 gene, which promotes the development of dendritic arbors, is transcriptionally repressed by sumoylated FOXP1, suggesting a potential molecular mechanism underlying FOXP1 function during neuronal development." (PMID 32719102, 2020). "Also the transcription factor Foxp1, which is known to have a prominent role in the CNS development and whose the expression is dysregulated in Huntington disease and Autism." (PMID 24804781, 2014). "Our finding may expand our understanding about the relationship of FOXP1 with autism." (PMID 23815876, 2013). "Moreover, we show that FOXP1 SUMOylation is required for regulation of CNTNAP2 expression, a candidate autism gene involved in dendritic maturation." (PMID 28408745, 2017). "Surprisingly, we also identified associations with SNPs at the P<10−4 level near several genes previously implicated in autism, although not in our analysis of proband effects: PCDH9 and FOXP1." (PMID 24204716, 2013). "Our data indicate that expressions of BDNF, Grm3, Foxp1, Auts2 and Shanks3 in the hippocampus are significantly induced by L-serine administration in GHRH-KO mice via changed expression of epigenetic markers, which may ameliorate impairment of memory and autism-related behavior." (PMID 36672612, 2022). "However, these FOXP1 mutations associated with ASD are rare; they may not apply to the pathogenesis of autism in general." (PMID 23815876, 2013).
autism spectrum disorder (33 papers, 2012 to 2025). A spectrum of developmental disorders that includes autism, and Asperger syndrome. "STR variations in the FOXP1 3ʹUTR have previously been implicated in cases of autism spectrum disorder (ASD)." (PMID 39741260, 2024). "bRGCs have enriched expression for Forkhead Box P1 (FOXP1), a transcription factor implicated in neurodevelopmental disorders (NDDs) such as autism spectrum disorder." (PMID 37540706, 2023). "In 2010, Hamdan and colleagues described two cases with ID and features of autism spectrum disorder (ASD) in whom a deletion involving FOXP1 and a sequence variant in FOXP1 were found." (PMID 33892622, 2021). "Interesting perspectives could arise by comparing animal studies with phenotypic analyses of human FOXP1 mutations associated with speech and language deficits but also autism spectrum disorder (ASD) associated variation in sensory feedback processing." (PMID 36931727, 2023). "Mutations in Foxp1 are causative for neurodevelopment disorders such as autism spectrum disorders." (PMID 36791184, 2023). "Mutations of FOXP1, a paralogue of FOXP2, are associated with a multifaceted neurodevelopmental syndrome encompassing phenotypes such as autism spectrum disorder (ASD) and/or cognitive impairments which often affect speech and language." (PMID 36931727, 2023). "Haploinsufficiency of FOXP1 leads to a neurodevelopmental disorder that among other features can include autism spectrum disorder (ASD)." (PMID 30753188, 2019). "In summary, we have shown that three patients with the same missense mutation (p.R525Q) in the forkhead box DNA-binding domain of FOXP1 results in global developmental delay, autism spectrum disorder, and characteristic dysmorphic features." (PMID 30385778, 2018). "Genome-wide association studies (GWASs) have demonstrated various risk loci for ASD such as FOXP1 at 3p13, ATP2B2 at 3p25.3 [Autism Spectrum Disorders Working Group of the Psychiatric Genomics Consortium, 2017(Autism Spectrum Disorders Working Group of The Psychiatric Genomics Consortium., 2017)]." (PMID 35655651, 2022). "In addition, human mutations in both FOXP1 and FOXP2 lead to severe speech and cognitive impairments and, both genes have also been linked to autism spectrum disorders." (PMID 34723967, 2021). "Reduced isolation-induced USVs have been reported in a number of genetic mouse models of neurodevelopmental disorders such as autism spectrum disorder (ASD), most recently reported for the Foxp1 model." (PMID 29186532, 2018).
diffuse large B-cell lymphoma (32 papers, 2006 to 2025). "FOXP1 also displayed increased activities and is associated with poor prognosis in diffuse large B-cell lymphoma and HCC." (PMID 39670859, 2025). "At the same time, other studies have reported an association between FOXP1 overexpression and inferior outcome in the context of hematologic malignancies such as follicular lymphoma and diffuse-large B-cell lymphoma." (PMID 31745703, 2020). "Although it is unknown whether expression of these truncated forms can have functional consequences in NB, short isoforms of FOXP1 have been shown to act like oncogenes in diffuse large B-cell lymphoma and in mucosa-associated lymphoid tissue lymphoma." (PMID 23991058, 2013). "For instance, the high expression of smaller isoforms of FOXP1 (60–65 kDa) in diffuse large B-cell lymphoma (DLBCL) are associated with a poor prognosis, while recurrent chromosomal translocations effect FOXP1 gene expression in B-cell non-Hodgkin lymphoma." (PMID 25663935, 2015). "pointed out that FOXP1 transcriptionally activates GINS1 expression to promote diffuse large B‐cell lymphoma development." (PMID 38652109, 2024). "Both FOXD1 and FOXP1 have been reported as activators of Wnt/β-catenin signaling in prostate cancer and diffuse large B cell lymphoma, respectively 28,29." (PMID 38684876, 2024). "In this regard, we demonstrated that FOXP1 is essential for tumorigenesis of the more aggressive form of Diffuse Large B-Cell Lymphoma, termed Activated B Cell (ABC-DLBCL)." (PMID 37507770, 2023). "It is well documented that FOXP1 is overexpressed with poor prognosis in diffuse large B-cell lymphoma (DLBCL), primary cutaneous large B-cell lymphomas (PCLBCL), follicular lymphoma and gastric mucosa-associated lymphoid tissue lymphoma (MALT) as an oncogene." (PMID 31815635, 2019). "Others loci are associated with hematological disorders such as CEBPA, FOXP1, MECOM and RHOH which promotes Acute myeloid leukemia, diffuse large B-cell lymphoma, myeloproliferative neoplasm and B-cell chronic lymphocytic leukemia respectively." (PMID 31105870, 2019). "FOXP2 shares partially overlapping normal tissue expression and functionality with FOXP1; an established diffuse large B-cell lymphoma (DLBCL) oncogene and marker of poor prognosis." (PMID 27224915, 2016). "The identified association among FOXP1, BCL2, and BCL6 indicates the possibilities of uncovering the development process in diffuse large B-cell lymphoma tumor cells." (PMID 23289441, 2013). "FOXP1 was known as a tumor promoter with a poor prognosis in follicular lymphoma, primary cutaneous large B-cell lymphomas (PCLBCL), gastric mucosa-associated lymphoid tissue lymphoma (MALT) and diffuse large B-cell lymphoma (DLBCL)." (PMID 36952469, 2023). "The FOXP1 (forkhead box P1) transcription factor is a marker of poor prognosis in diffuse large B-cell lymphoma (DLBCL)." (PMID 26500140, 2016). "For example, FOXP1 inhibits the behaviour of immune activation and the expression of MHC class II in diffuse large B-cell lymphomas." (PMID 36160018, 2022). "Our study revealed that non-IG rearrangements of FOXP1 are usually acquired during clinical course of various lymphoma subtypes, including diffuse large B cell lymphoma, marginal zone lymphoma and chronic lymphocytic leukemia, and correlate with a poor prognosis." (PMID 24416450, 2014).
ovarian carcinoma (28 papers, 2012 to 2025). A malignant neoplasm originating from the surface ovarian epithelium. "For instance, downregulation of FOXP1 is associated with aggressive tumor behavior, resulting in poor prognosis in colorectal neoplasia, prostate cancer, endometrial, ovarian cancer, and renal cell carcinoma." (PMID 38279090, 2024). "FOXP1 expression was an independent risk factor associated with chemotherapy resistance and the prognosis of patients with ovarian cancer." (PMID 26910918, 2017). "FOXP1 has been reported to be associated several human malignancies, including endometrial cancer, lung cancer, head and neck cancer, prostate cancer, renal cell carcinoma, ovarian carcinoma, osteosarcoma, hepatocellular carcinoma and B cell lymphoma." (PMID 37507770, 2023). "Furthermore, adoptive transfer of tumor-primed FoxP1-deficient T cells enhanced survival in mouse models of ovarian cancer and sarcoma, relative to wild-type T cell transfer." (PMID 36829573, 2023). "Furthermore, this allele weakens the binding motif of FOXP1, a transcriptional repressor that appears to act as an oncogene in ovarian cancer." (PMID 29029385, 2017). "For instance, knocking out XIST can inhibit autophagy and carboplatin resistance in ovarian cancer cells through the FOXP1/AKT pathway." (PMID 40308577, 2025). "FOXP1 also promoted the development of drug resistance in patients undergoing treatment for ovarian cancer." (PMID 40672953, 2025). "FOXP1 functions as an oncogene in epithelial ovarian cancer cells by promoting the CSC-like characteristics, while its overexpression led to an up-regulated expression of ABCG2, OCT4, NANOG, and SOX2 genes and protected cells against apoptotic cell death." (PMID 37189618, 2023). "miR-374b suppresses the migration and invasion of bladder cancer cells by targeting ZEB2, an EMT-inducing transcription factor, and suppresses cell proliferation, migration, and EMT in ovarian cancer by targeting FOXP1." (PMID 32674274, 2020). "In xenotransplantation of A2780 ovarian cancer cells into nude mice, knockdown of FOXP1 expression significantly decreased tumor size." (PMID 26654944, 2016). "In this study, we explored the role of FOXP1 in ovarian cancer by examining the effects of FOXP1 expression on ovarian cancer cells." (PMID 26654944, 2016). "Taken together, the current study demonstrated that FOXP1 functions as an oncogene by promoting CSC-like characteristics in ovarian cancer cells." (PMID 26654944, 2016). "In the current study, we demonstrated that FOXP1 functions as an oncogene in epithelial ovarian cancer cells by promoting the CSC-like characteristics including spheroid formation, cell proliferation, cell migration, drug resistance, and tumorigenic potential." (PMID 26654944, 2016). "In the current study, we show that FOXP1 promotes cancer stem cell-like characteristics in ovarian cancer cells." (PMID 26654944, 2016). "Previous studies of FOXP1 in ovarian cancer have reported correlation of expression with the degree or malignancies of ovarian cancer along with contradictory observations." (PMID 26654944, 2016). "Taken together, the results suggest that FOXP1 expression is positively correlated with expression of genes related to CSC-like characteristics in in ovarian cancer cells." (PMID 26654944, 2016). "A set of eight biomarkers: NKIRAS1/RPL15, THRB, RBPS3 (CTDSPL), IQSEC1, NBEAL2, ZIC4, LOC285205 and FOXP1, was identified as the most prominent set capable to detect both early and late stages of ovarian cancer." (PMID 23202957, 2012). "Moreover, the inhibition of FOXP1 led to a decrease in the proliferation of cancer stem cells in ovarian cancer." (PMID 40169859, 2025). "Equally, a recent study has provided evidence that the downregulation of autophagy-related gene 14 (ATG14) and Forkhead box protein P1 (FOXP1), a well-known transcription factor with oncogenic effects in ovarian cancer cells, can enhance the sensitivity of ovarian cancer cells to cisplatin." (PMID 38994937, 2024).